IL1B (interleukin 1 beta)
Diseases named in the same sentence as IL1B in open-access papers (continued):
Sharing a sentence is not in itself a finding about the gene and the disease.
depression (continued). "Patients with depressive disorders were reported to have a higher serum concentration of inflammatory markers, including interleukin (IL)-6, tumor necrosis factor (TNF)-α and IL-1β, compared with those without depressive disorders." (PMID 31765424, 2019). "In conclusion, our meta-analysis found that elderly with depression had elevated peripheral levels of IL-1β, IL-6 but not CRP and TNF-α, and elderly with Alzheimer’s disease only had increased peripheral levels of blood IL-1β." (PMID 30104698, 2018). "Injection of interleukin-1β (IL-1β) receptor antagonist in the CNS ventricular space reduced the depressive behavior and KMO mRNA levels, but did not change the allodynia, revealing the role of IL-1β in depression but not in the pain mechanism." (PMID 30544839, 2018). "The domination of M1 phenotype exaggerates neuroinflammation through releasing pro-inflammatory cytokines, such as IL-1β and TNF-α, but suppresses anti-inflammatory cytokines like IL-10 and TGF-β, which may contribute to the etiology of depression." (PMID 30248907, 2018). "In this meta-analysis, we found that elderly with depression had significantly higher peripheral levels of IL-1β (p = 0.026), IL-6 (p < 0.001) but not TNF-α (p = 0.351) and CRP (p = 0.05)." (PMID 30104698, 2018). "Collating these findings, it seems likely that IL-1β-activated p38 MAPK cascades may participate in the ameliorative effects of curcumin on neuronal apoptosis and depression-like behaviors in our CUMS rats." (PMID 30666189, 2018). "In addition, resveratrol supplementation reduces levels of pro-inflammatory cytokines (IL-1β, IL-2, IL-4, IL-6, TNF-α) in animal models of depression." (PMID 30200269, 2018). "A significant increase in plasma IL-6, IL-1β, and TNF-α concentrations, indicating the inflammatory processes in major depressive disorder, thus supporting the cytokine hypothesis of major depression, was recorded in many studies." (PMID 30533439, 2018). "Patients with mood disorder and anxiety disorder had higher levels of IL-1β, but we found no systematic relationship between level of depression and level of the measured cytokines." (PMID 29631540, 2018). "On the other hand, studies in animal models have revealed that IL-1β acts as a potent stimulant of the serotonin transporter mediated by p38 MAPK, increasing the uptake of serotonin, which is in accordance with the physiopathology of depression." (PMID 30662368, 2018). "Of note, the CUMS procedure induced a nonsignificant change in serum IL-1β levels, which was indicative of regional inflammation rather than systemic inflammation in depression." (PMID 29853787, 2018). "More importantly, studies have clearly shown that NF-κB increased IL-1β and TNF-α expression in the hippocampus and frontal cortex during stress and regulated neurogenesis in the hippocampus which were closely related with depression." (PMID 29765402, 2018). "Rats with depression-like phenotype displayed higher levels of pro-inflammatory cytokines (e.g., interleukin (IL)-1β, IL-6) as well as imbalance of pro/anti-inflammatory cytokines compared with rats without depression-like phenotype and sham-operated rats." (PMID 28600519, 2017). "Our findings indicate significant and positive correlations of spiritual pain with stress, depression, and religious coping, but non-significant correlations of spiritual pain with loneliness, salivary cortisol, and salivary IL-1β." (PMID 27417804, 2015). "Elevated IL-1β levels in subjects with major depression, in comparison to non-depressive controls, were observed only in studies including subjects older than 40 years of age and studies rated as lower quality." (PMID 26065825, 2015). "Depression has been characterised as an increased inflammatory status (inflammaging) including elevated levels of pro-inflammatory cytokines, including IL6, TNFα and IL1β." (PMID 25628751, 2014).
depression (continued). "Numerous studies indicate that proinflammatory cytokines (IL-1β, IL-6, TNF-α, IFN-α (interferon α), IFN-γ, soluble receptor for IL-6, antagonist of the receptor for IL-1) are crucial factors in etiopathogenesis of depression." (PMID 25530618, 2014). "Interestingly, it has been determined that pro-inflammatory molecules, such as IL-1β and TNFα, induce depression-like symptoms, and reduction of their circulating levels could diminish depressive symptoms, suggesting linkage between inflammation and depression." (PMID 25402828, 2014). "Similarly, most of the studies in the field are focused on definite cytokines including interleukin- (IL-)1β, IL-6, and tumor necrosis factor-α (TNF-α) since the changes in circulating IL-1β, IL-6, and TNF-α were revealed in patients with major depression." (PMID 24999483, 2014). "There was a significant correlation between change in IL-1β and depression symptoms for the 16 KKW group, but not the 4 KKW group." (PMID 23382717, 2013). "Increased IL-1β, IL-6, and TNF-α in post-mortem PFC were also found in teenaged individuals that died by suicide, although in this study not all tissue had come from individuals that had been diagnosed with major depression." (PMID 23675319, 2013). "The proportion of IL-1β-positive cells in the anxiety-depression IBS-D group (0.310±0.223) was significantly higher than that in the non-anxiety-depression IBS-D group (0.234±0.124; P<0.05)." (PMID 23935726, 2013). "In vivo, a lipopolysaccharide (LPS)-induced mouse model of depression was established to assess the effects of WIS32 intervention on behavioral phenotypes, hippocampal neurochemicals (5-HT and BDNF), and serum pro-inflammatory cytokines (TNF-α, IL-1β, and IL-6)." (PMID 42238885, 2026). "This study did not provide direct evidence on how IL-1B induces depression in PLWH." (PMID 40313235, 2025). "In addition, DHM achieves synergistic relief of pain and depression symptoms by downregulating P2X7 receptor expression, blocking the ATP-gated ion channel-mediated ERK1/2 phosphorylation cascade, and reducing TNF-α and IL-1β levels." (PMID 40740995, 2025). "However, IL-6, IL-18, and IL-1β levels are not significantly correlated with depression in patients with CHD and STEMI." (PMID 41301929, 2025). "It has been shown that IL-1β and IL-18 released upon the activation of NLRP3 inflammatory vesicles may be key molecules in triggering the immune response in depression and further exacerbate the pathological process through Gasdermin D (GSDMD)-mediated cellular pyroptosis response." (PMID 40497971, 2025). "Besides, individuals diagnosed with MDD had higher levels of nuclear factor kappa B (NF-κB) and pro-inflammatory cytokines, including interleukin-6 (IL-6) and interleukin-1β (IL-1β), when compared to the control group without depression." (PMID 38890689, 2024). "In the CUMS model of depression, quercetin significantly reduces the behavioral signs of stress, and raises superoxide dismutase, catalase and GSH levels while reducing lipid peroxidation and attenuating the expression and levels of the proinflammatory markers IL-6, TNF-α, IL-1β, and COX-2." (PMID 39150032, 2024). "One study reported a significant increase in the serum levels of TNF-α, IL-1β and IL-6 in patients with AD and depression, compared to AD patients without depression, with strong inverse correlations between the MMSE scores and pro-inflammatory cytokine levels." (PMID 39526037, 2024). "Additionally, heightened microglia activation has been observed in the white matter region of the dorsal anterior cingulate gyrus in suicidal patients with depression, although the expression levels of IL-1β, TNF-α, and IL-10 were not elevated." (PMID 39654612, 2024).
depression (continued). "Animal studies demonstrated that prolonged Sb exposure increased levels of inflammatory factors (interleukin-1β (IL-1β), IL-6, and TNF-α) and pro-oxidant substances (glutathione peroxidase, malondialdehyde), indicating that Sb boosts inflammatory responses, closely tied to depression." (PMID 39691784, 2024). "IL1B was higher in those with AD regardless of depression status." (PMID 38175420, 2024). "Studies have shown that inflammatory factors IL-1β, IL-6, TNF-α, and CRP are elevated and anti-inflammatory factors IL-4, IL-8, and IL-10 are decreased in peripheral and cerebrospinal fluid and correlate with patients’ symptoms and disease duration in depression and anxiety." (PMID 36624089, 2023). "Notably, MSCs have the ability to downregulate the expression of the proinflammatory cytokines IL-1β, IL-6, and TNF-α, which is one of the major reasons that contribute to the development of depression, as discussed in the cytokine hypothesis." (PMID 36986674, 2023). "In addition, high serum levels of IL-1β stimulate the production of pituitary adrenocorticotropic hormone (ACTH), hypothalamic adrenocorticotropic hormone-releasing hormone (CRH), and adrenal steroids, indirectly leading to depression." (PMID 37692303, 2023). "However, TNF-α, IL-1B, and IL-6 secretion in DD group was significantly enhanced than that in depression and diabetes group (P < 0.05, P < 0.01); CX3CR1 blocker treatment of DD group significantly reduced the levels of TNF-α, IL-1B, and IL-6 in hippocampus of all groups (P < 0.05, P < 0.01)." (PMID 36072409, 2022). "Whether the participants had a depression or not, in average the FA was less with higher IL-1β cytokine concentration." (PMID 36261698, 2022). "Similarly, elevated expressions of IL-2, IL-10, IL-1β, TNF-α, and/or IFN-γ may be detected in depression, schizophrenia, bipolar disorder, PTSD, and suicidal ideation." (PMID 34648616, 2022). "In the chronic unpredictable mild stress (CUMS)-induced depression mouse model, researchers found significantly elevated levels of IL-1β protein in serum and hippocampus, but not in NLRP3 knockout mice, probably because NLRP3 knockout inhibited MAPK pathway and NF-κB pathway activation." (PMID 35937897, 2022). "first reported the association of cytokine polymorphisms with PSD, showing that patients with polymorphisms of anti-inflammatory cytokines IL-4 and IL-10 rather than pro-inflammatory cytokines TNF-α, IL-1β, IL-6 and IL-8 had an increased propensity to develop depression in the acute phase of stroke." (PMID 36225923, 2022). "Furthermore, in an LPS-induced rat model of depression, administration of ketamine and GTS-21([3-(2,4-dimethoxybenzylidene) anabaseine], a selective α7 nAChR agonist) was shown to reduce the levels of IL-1β, IL-6, and TNF-α compared to the group of rats treated with LPS alone." (PMID 34948222, 2021). "Pathological IL-1β has been indicated to inhibit glutamate reuptake and lead to N-methyl-D-aspartate (NMDA)-mediated excitotoxicity by reducing expression of the presynaptic glutamate transporter, resulting in neuronal damage and structural abnormalities in depression." (PMID 34900691, 2021). "Moreover, in our subgroup analysis, patients with depressive symptoms had specific overexpression of IL-1β while patients without depression did not, and the evaluated IL-1β was also found with significant positive association with depressive symptoms." (PMID 34900691, 2021). "Furthermore, interleukin (IL)-1β production in the brain in a chronic stress mouse model was found to play a key role in chronic stress-induced depression, and IL-1 receptor type 1 (IL-1R) knockout mice were not susceptible to these effects." (PMID 33790733, 2021). "Recently, several studies have investigated the influence of peripheral proinflammatory cytokines (e.g., IL-6, IL-1β, and TNF-α) on neuronal synaptic plasticity, neurogenesis, and neuromodulation, which play critical roles in the initiation, relapse, and progression of depression." (PMID 33466877, 2021).
depression (continued). "Furthermore, IL1β activates the HPA axis and can lead to glucocorticoid receptors functional resistance, a mechanism widely investigated in the relation between inflammation and depression." (PMID 35002816, 2021). "Similarly, the Genome-Based Therapeutic Drugs for Depression (GENDEP) project showed that the mRNA expression of inflammation-related genes, such as IL-1b, macrophage inhibiting factor (MIF) and tumor necrosis factor (TNF) are higher in non-responders depressed patients before treatment." (PMID 34103475, 2021). "EA decreased the expression of P2Y12 and IL-1β as well as the activation of microglia, suggesting that EA downregulated the expression of P2Y12, weakened the activation of microglia, and then inhibited IL-1β expression in the mPFC, thus relieving hyperalgesia and depression in IBD mice." (PMID 34930362, 2021). "The cooccurrence of chronic pain and depression is intimately related to increases in TNF-α, IL-1β, and IL-6 in target structures such as the PFC, ACC, amygdala and hippocampus, emphasizing the involvement of glial activation in limbic regions involved in pain and depression processing." (PMID 32849076, 2020). "High levels of IL-1β, IL-2, and TNF-α can induce neuronal apoptosis, inhibit neuronal differentiation, abolish synaptic transmission, and counteract either the induction or maintenance of long-term potentiation, thus leading to an impairment of learning and further worsening of depression symptoms." (PMID 32849818, 2020). "Elevated levels of proinflammatory cytokines, especially interleukin-1β (IL-1β), interleukin-6 (IL-6), and tumor necrosis factor alpha (TNF-α), can interact with the neuroendocrine function and influence neuronal function, which has been reported in depression." (PMID 32596383, 2020). "Rats that show increased depression-like behaviors after neuropathic injury display higher levels of proinflammatory cytokines (e.g., IL-1β, IL-6) as well as imbalance of pro/anti-inflammatory cytokines, compared with rats without depression-like phenotype and sham-operated rats." (PMID 29876878, 2019). "In addition, IL-10 decreased in mPFC and BA, while IL-1β and TNF-α protein expression increased in mPFC, BA, and VH on POD 45, which indicated a CNS shift to pro-inflammatory profile at the time when anxiety- and depression-related behaviors were observed." (PMID 30208926, 2018). "Compared with controls, IL-1β (pooled standardized mean difference [SMD]: 0.642; 95% confidence interval [CI]: 0.078–1.206; significant heterogeneity: I2 = 86.28%) and IL-6 (pooled SMD: 0.377; 95% CI: 0.156–0.598; significant heterogeneity: I2 = 88.75%) were significantly elevated in depression." (PMID 30104698, 2018). "The activated M1 phenotype expresses CD11b, CD68, and pro-inflammatory cytokines, including interleukin (IL)-1β, tumor-necrosis factor (TNF)-α, and IL-6, which have been extensively reported to induce oxidative stress, neuronal damage, neurotransmitter dysfunction, and depression-like behavior." (PMID 30248907, 2018). "Our hypothesis was that elderly with depression or Alzheimer’s disease had higher levels of IL-1β, IL-6, TNF-α and CRP than controls without psychiatric disorders." (PMID 30104698, 2018). "Interestingly, higher serum levels of IL-1β and IL-6 in the rat with depression-like phenotype were normalized after a single dose of ketamine." (PMID 28600519, 2017). "Moreover, we observed that 3 of 8 depression rats regarded as ketamine non-responder group displayed lower serum levels of IL-1β and IL-6." (PMID 28600519, 2017). "No consistent evidence support a link between IL-1β and depression (14 studies), which may in part be related to the very low concentrations of this cytokine in peripheral blood and a lack reliable detection methods." (PMID 26631274, 2016).
depression (continued). "Similar to the findings in CP/CPPS patients, elevated levels of IL-1α, IL-1β, IL-4, IL-13, and TNF-α were observed in CP/CPPS rat prostates, and these elevated cytokine levels showed a positive trend in their correlation with anxiety, depression, and memory impairment." (PMID 27334333, 2016). "Thus, we next analyzed the expression levels of the genes encoding for three of the most relevant pro-inflammatory cytokines, IFN-γ, IL-1β, and TNF, for the anti-inflammatory cytokine IL-10 and for the enzyme iNOS, all previously addressed in studies on the etiology of depression." (PMID 26696854, 2015). "Furthermore, immunohistochemistry revealed significant differences in the positive expression of IL-1β and IL-10 between the anxiety-depression and non-anxiety-depression IBS-D groups." (PMID 23935726, 2013). "As IL-1β release can initiate microglia and astrocyte activation leading to the downstream synthesis of other proinflammatory cytokines in CNS (e.g., IL-6), the chronic microglial activation reported in depression may activate a negative feedback to supress IL-1β." (PMID 40179065, 2025). "Similarly, to IL-1β and IL-8, the analysis of IL-4 demonstrated that its concentration levels increased as depression became more severe, regardless of whether with or without concomitant PTSD." (PMID 35326343, 2022). "As mentioned in the previous section, pro‐inflammatory cytokines, such as IL‐1β, TNF‐α, IFN‐γ and TGF‐β, can cross the BBB and initiate or modulate astrogliosis, suggesting that stress‐induced exacerbated activation of these glial cells may contribute to depression pathogenesis." (PMID 31421056, 2021). "According to the present investigation, this mainly involves IL-1β, CRH, and dopamine (and to a lesser extent serotonin) which could influence the synbiotic-induced reduction in perceived levels of anxiety and stress, fatigue and depression, as well as the objective improvement in sleep quality." (PMID 33923663, 2021). "In addition, IL-1β is a potent modulator of corticotrophin-releasing hormone which produces heightened hypothalamic-pituitary-adrenal axis activity characterized by increases in adrenocorticotropic hormone (ACTH) and CORT, both of which are reported to be generally elevated in major depression." (PMID 26417153, 2015). "Consistent with the suggestion that violent and/or impulsive behaviors may be linked to neuropsychiatric conditions, increased IL-1β, IL-6, and TNF-α in post-mortem PFC were observed in teenaged individuals that died by suicide, irrespective of whether they had been diagnosed with major depression." (PMID 25565946, 2014). "In clinical populations, IL-6, IL-1β, and CRP were elevated among women with depression, whereas these markers were not elevated in men, and rather men displayed elevated levels of IL-17." (PMID 40305313, 2025). "Clinical evidence has demonstrated significantly higher concentrations of inflammatory cytokines, such as IL-1β, IL-6 and TNF-α activated by NLRP3 in the cerebrospinal fluid and serum of patients with depression compared to non-depressed individuals." (PMID 37474898, 2023). "In humans, the levels of pro-inflammatory cytokines IL-1β, IL-6, and TNF-α were reported to be significantly higher in the post-mortem brains of suicided patients with depression than in those of matched non-psychiatric controls." (PMID 37273278, 2023). "There is ample evidence to support the association between increased cortisol and pro-inflammatory cytokines (IL-1β, IL-6, IL-8, TNF-α) in negative mood conditions, stress levels, anxiety, and depression." (PMID 36986501, 2023). "Another non-significant negative correlation (p = 0.07) was noted between IL-1β gene expression and the HADS depression score (r = −0.325)." (PMID 37238223, 2023). "Elevated IL-1β mRNA and protein levels were also found in the prefrontal cortex in a chronic mild stress (CMS)-induced depression model in rats, while no similar phenomenon was observed in blood." (PMID 35937897, 2022).